CHD4 (chromodomain helicase DNA binding protein 4)
Diseases named in the same sentence as CHD4 in open-access papers (continued):
Sharing a sentence is not in itself a finding about the gene and the disease.
infection (4 papers, 2016 to 2024). The state of being infected such as from the introduction of a foreign agent such as serum, vaccine, antigenic substance or organism. "CHD4 protein levels were assessed at day 0 and 8 upon infection (at the beginning and the end of the proliferation assay)." (PMID 27779108, 2016).
cardiovascular disorder (1 paper, 2026). A disease involving the cardiovascular system. "In contrast, other variants located in the N- and C-terminal regions were more often associated with vascular phenotypes, suggesting domain-specific roles of CHD4 in cardiovascular disease." (PMID 41756679, 2026).
colorectal (1 paper, 2019). "By in vitro studies, based on cell line models, we also demonstrated that, the overexpression of CHD4 induced radio-resistance in microsatellite instability-high (MSI-H) colorectal cells (CRCs)." (PMID 31438571, 2019).
heart disease (1 paper, 2020). "For example, while CDK13, CHD4, KDM5A, and SCN10A are related to familial heart disease, CFH, DGUOK, and POLE are related to familial vascular disease." (PMID 31941532, 2020).
CHD4 also shares sentences with these, for which no sentence is quoted: myositis (7 papers); neurological disorders (3); cardiomyopathies (2); clear cell carcinoma (2); developmental delay (2); endometriosis (2); inflammatory myopathy (2); interstitial lung disease (2); liver cancer (2); migraine (2); moyamoya angiopathy (2); Myalgia (2); Neurodevelopmental delay (2); adenocarcinoma (1); anaplastic thyroid carcinomas (1); ANCA-associated vasculitis (1); ataxia telangiectasia (1); Chiari malformation (1); chronic myelogenous leukemia (1); ciliopathies (1); congenital hydrocephalus (1); connective tissue disease (1); deafness (1); ductal carcinoma (1); Ebstein anomaly (1); endometrial atypical hyperplasia (1); familial amyloidosis (1); Fanconi anemia (1); fibromyalgia (1); genetic disorder (1).
A further 27 diseases each share a sentence with CHD4 in 1 paper.